TNF (tumor necrosis factor)
Diseases named in the same sentence as TNF in open-access papers (continued):
Sharing a sentence is not in itself a finding about the gene and the disease.
psoriasis (continued). "Furthermore, it has been reported that neutrophil infiltration, a hall-mark of psoriasis, is markedly reduced following treatment with IFN-γ/TNF-α-preconditioned MSCs (MSCs-IT)." (PMID 40906403, 2025). "Similarly, in psoriasis, CD4+ T cells are activated by dendritic cells presenting self-antigens, releasing proinflammatory cytokines such as TNF-α, IL-17, and IL-22." (PMID 40310305, 2025). "In cellular models, Etoposide demonstrated promising therapeutic effects by significantly downregulating the expression of psoriasis-related keratinocytes marker genes (KRT6, KRT16) and CD-related inflammatory cytokines (IL6, IL8, TNF-α), highlighting its potential in treating psoriasis and CD." (PMID 40406126, 2025). "Thus, beyond recommendations favoring monoclonal antibodies against TNF in patients with a history of recurrent uveitis or active IBD and preferring an IL-17i in patients with significant psoriasis, the choice of therapeutic agent is empirical." (PMID 40137452, 2025). "In IMQ-induced psoriasis mice, Lactiplantibacillus plantarum GMNL-77 reduced the proportion of IL-17A+CD4+ T cells and decreased the expression of inflammatory factors such as TNF-α, IL-23, and IL-17A, leading to amelioration of erythematous and scaly lesions." (PMID 41425939, 2025). "Remarkably, our data demonstrated a specific impairment in the differentiation of Tc17 cells within the epidermis of Lztr1-deficient mice, accompanied by decreased expression of T activation-related proteins in psoriasis, such as CTLA-4, PD-1, IL22 and TNF-α 12,38,39." (PMID 41162356, 2025). "Similar to AD, psoriasis involves keratinocyte-driven activation of the NF-κB, JAK/STAT, and MAPK, which stimulate the production of pro-inflammatory cytokines such as IL-1β, IL-6, and TNF-α." (PMID 41479908, 2025). "Notably, HIF1A, IL-6, TNF, and IFNG were co-modulated by more than four BPs, indicating their central role in the mechanism of action of SHTLS in psoriasis treatment." (PMID 40507893, 2025). "IFN-γ, a type II interferon, is thought to contribute to the pathological intestinal inflammation seen in irritable bowel disease (IBD) and TNF is widely recognised for its involvement across autoimmune conditions such as IBD, arthritis, psoriasis, and systemic lupus erythematosus." (PMID 39850904, 2024). "Golimumab is the only anti-TNF drug approved for psoriatic arthritis, but not currently for psoriasis." (PMID 39065754, 2024). "This phenomenon includes worsening of pre-existing psoriasis or onset of new psoriasiform eruption in a patient with no prior history of psoriasis or psoriatic arthritis in the setting of anti-TNF use." (PMID 39403182, 2024). "The prevalence of psoriasis in patients with CD and UC is 3.6% and 2.8%, respectively, while the prevalence of paradoxical psoriasis in IBD is 6.7%, stressing the impact of therapy with anti-TNF-α drugs on the development of this disease." (PMID 38398332, 2024). "In the early stages of psoriasis, nucleic acids and antimicrobial peptides activate innate immune cells, including plasmacytoid dendritic cells (pDCs) and macrophages, leading to the production of IFN-α and TNF-α." (PMID 39684717, 2024). "Given the central role of TNF-α, the introduction of therapies that specifically target TNF-α, including infliximab, adalimumab, etanercept, and others, have significantly transformed the overall landscape of psoriasis management." (PMID 39063004, 2024). "This improvement in CFR was associated with reduced levels of TNF and high-sensitivity C-reactive protein (CRP), although it did not correspond to changes in the Psoriasis Area and Severity Index (PASI)." (PMID 38522049, 2024). "Considerable pro-inflammatory cytokines, including tumor necrosis factor (TNF)-α, type I interferon (IFN), and notably interleukin (IL)-17/23, emanating from cutaneous lesions in psoriasis patients, elicit an aberrant immune response within the pulmonary system via the circulatory system." (PMID 38403646, 2024).
psoriasis (continued). "Moreover, FCGR3A was found to interact with known therapeutic targets of psoriasis such as CD2, Tumor necrosis factor (TNF), Integrin subunit alpha L (ITGAL), and IL17A." (PMID 39883516, 2024). "Immune-related cells including dendritic cells (DCs) and T helper (Th) 17 cells, along with Toll-like receptors(TLRs) and cytokines such as interferon (IFN)-α, tumor necrosis factor (TNF)-α, IFN-γ, Interleukin(IL)-12, IL-22, IL-23, and IL-17, are responsible for the pathogenesis of psoriasis." (PMID 38347543, 2024). "Th1 cells are the main source of pro-inflammatory cytokines such as TNF-α, IFN-γ, and IL-2 in the peripheral blood and lesion areas of psoriasis patients, while Th2 cells mainly secrete the cytokine IL-4, which significantly increases in patients with erythrodermic psoriasis." (PMID 38255845, 2024). "A study of 81 patients with psoriasis diagnosed with nail disorders stated that the prevalence of onychomycosis in patients with psoriasis receiving conventional and anti‐TNF‐α therapies was higher than that in those not receiving treatment." (PMID 38660962, 2024). "Furthermore, α-humulene and torilin from Cnidi fructus were identified as targeting psoriasis-related proteins, including IL1B, TNF, NOS2, and NFKBIA." (PMID 39590306, 2024). "Furthermore, TNF-α, interferon-γ (IFN-γ), IL-6, and IL-22 have also been reported to be increased in psoriasis." (PMID 39109246, 2024). "hs-CRP, IL-17, and TNF-α in psoriasis patients with and without atherosclerosis across different levels of psoriasis severity." (PMID 39104857, 2024). "The findings indicated that TNF-α inhibitors more effectively reduced coronary inflammation, evidenced by significant reductions in CIMT, coronary plaques (measured by CCTA), CRP, and Psoriasis Area and Severity Index (PASI) scores compared to phototherapy." (PMID 39739136, 2024). "A preliminary comparative study suggested that the use of ixekizumab in psoriasis patients did not affect body weight and proposed it as a more favourable decision for overweight patients receiving anti-TNF-alpha therapy." (PMID 38185620, 2024). "Tumor necrosis factor-alpha (TNF-a) belongs to a class of proinflammatory cytokines overexpressed during inflammation, leading to the initiation and persistence of inflammatory diseases such as autoimmune diseases (e.g., psoriasis)." (PMID 38951806, 2024). "The symptoms of psoriasis, such as thickness, erythema, and scaling, and the inflammatory cytokines levels of T-helper (Th)-17-specific cells, such as IL-17 and IL-22, and Th-1-specific cells, such as TNF-α and IL-1β, are reduced by treatment with L-EO in an IMQ-induced psoriasis mouse model." (PMID 38791435, 2024). "The non-canonical pathway is activated by specific TNF cytokines and contributes selectively to psoriasis pathogenesis." (PMID 38892253, 2024). "Over the years, several studies have reported increased levels of TNF, TNFR1, and TNFR2 observed in psoriatic lesions, which are produced by various cellular populations involved in the pathophysiology of psoriasis, such as keratinocytes, dendritic cells (DCs), and NKT, Th1, Th17, and Th22 cells." (PMID 38793117, 2024). "Psoriasis is a chronic inflammatory immune-mediated dermatosis that involves both Th1 and Th17 cells, with Th1 cells secreting IFN-γ and TNF-α and Th17 cells secreting IL-17, IL-22 and TNF-α." (PMID 38914981, 2024). "Nevertheless, targeting Th1 cytokines such as IFN-γ and TNF-α alone was not shown to improve psoriasis outcomes." (PMID 39337637, 2024). "However, this system also interacts with immune responses, particularly by influencing the activity of T-cells and cytokines such as IL-17, IL-23, and tumor necrosis factor (TNF)-alpha, which are critical components in the pathogenesis of psoriasis." (PMID 39364528, 2024).
psoriasis (continued). "Dysregulated levels of adipokines, cytokines (such as TNF-α, VEGF, IL-6, IL-8, and IL-12), and inflammatory immune response, driven by Th1, Th19, and dysfunctional adipose tissue; were shown to be responsible for the progression of psoriasis and MetS." (PMID 38683749, 2024). "TNF inhibitors seem to be the safest and most studied biological drugs for use during planned pregnancy, pregnancy, or breastfeeding in the treatment of psoriasis, given their nonexistent or minimal placental transfer." (PMID 39029031, 2024). "However, biologic therapies targeting key inflammatory cytokines such as tumor necrosis factor-alpha (TNF-α), interleukin-17 (IL-17), and interleukin-23 (IL-23) have significantly advanced the management of moderate to severe psoriasis​." (PMID 39463646, 2024). "Moderate-to-severe psoriasis is typically managed with systemic non biologic therapies (like methotrexate and cyclosporin), targeted therapies (such as the oral PDE4 inhibitor apremilast), and biological therapies targeting TNF-α, IL 12/23, IL-17, or IL-23." (PMID 39549073, 2024). "Furthermore, recent studies have found that TNFα can induce keratinocyte pyroptosis through the Caspase3/GSDME pathway, providing new insights into the progression of psoriasis." (PMID 39595526, 2024). "This study aims to investigate the modulatory effects of IFN-γ and a proinflammatory cytokine mix (5MIX: IL-1α, IL-17A, IL-22, OsM, and TNF-α) on keratinocyte antigen-presenting capacities and their interactions with CD4+ lymphocytes, with a specific focus on their role in psoriasis pathogenesis." (PMID 39769151, 2024). "The association of NLRP3 (rs10754558) gene polymorphism, TNFα and CRP with disease severity and their role as biomarkers for response to different systemic therapy in psoriasis have not been explored to date." (PMID 38965465, 2024). "Antibodies that inhibit the tumor necrosis factor (TNF), the interleukin (IL) ‐17, the IL‐23 and the IL‐12/IL‐23 axes have been proven effective in inducing primary endpoints in randomized controlled trials on psoriasis." (PMID 38345289, 2024). "For instance, S100A15-L exhibits a more pronounced response to pro-inflammatory Th1 cytokines, such as TNF-α, IFN-γ, and IL-1β, than S100A15-S, which may explain its ~25 times greater expression than S100A150-S in acne lesions, as suggested for psoriasis." (PMID 39744637, 2024). "Last but not least, TBTDC NP-PDT attenuated IMQ-induced up-regulation of inflammatory cytokines, including TGF-β1, IL-1β, IL-17, IL-23, TNF-α, IFN-γ, IL-6, and IL-22, which are important proinflammatory cytokines involved in psoriasis pathogenesis in the skin lesions of mice." (PMID 39109246, 2024). "Currently, although biologics targeting TNF-α, IL-12/IL-23 or IL-17A are highly effective in the treatment of psoriasis, not all patients respond in the same manner." (PMID 38566145, 2024). "TNF-α inhibitors and JAK inhibitors may be underutilized in psoriasis patients with comorbidities with shared pathogenesis." (PMID 38957840, 2024). "Tumor necrosis factor-α (TNF-α), interferon-γ (IFN-γ), interleukin (IL)-23/IL-17A, and IL-22 are the primary immunological molecules responsible for keratinocyte proliferation, inflammation, and cytokine infiltration in psoriasis." (PMID 37446403, 2023). "Both forms of LL37 tended to induce secretion of TNF-α by MNCs from patients with psoriasis, but not by MNCs from HDs." (PMID 38173716, 2023). "Further, the laboratory indicators reflecting the treatment response to TNF-α inhibitors in psoriasis have not been established." (PMID 36769622, 2023). "TNF and IL17RA have been shown to have synergistic effects in psoriasis, and both are approved by the U.S. Food and Drug Administration as pharmacotherapeutic targets in psoriasis." (PMID 36979355, 2023).
psoriasis (continued). "It induces the expression of other psoriasis signature genes, such as IL36G, S100A15, DEFB4A, S100A9, CXCL8, TNIP3 (coding TNF-α-induced-protein 3 or TNFAIP3), and LCN2 (by synergy of IL-17C with TNF-α) in keratinocytes." (PMID 36928592, 2023). "A 6–8-week oral administration of Bifidobacteria infantis 35624 in psoriasis patients not receiving any anti-psoriatic treatment significantly decreased the plasma levels of C-reactive protein and TNF-α." (PMID 37895330, 2023). "Although IL-17A, IL-23, and TNF-α are key cytokines in psoriasis, their subcutaneous injection into mice did not induce scratching behavior." (PMID 37834081, 2023). "Serum TNF-α was found to be significantly higher in those with psoriasis than those without; however, majority of these studies report that its correlation with PASI scores was not significant." (PMID 37546687, 2023). "Studies found that cytokines secreted by T cells associated with psoriasis are almost Th1 related cytokines (IL-2, IFN-γ, and TNF-a), but not Th2 type cytokines (IL-4 and IL-10)." (PMID 37942312, 2023). "Angiopoietin-like protein 4 (ANGPTL4) is highly expressed in the skin lesions of psoriasis patients, ANGPTL4 recombinant protein promotes psoriasis-like skin lesions in mice, and the knockout of ANGPTL4 inhibits keratinocyte growth and expresses cytokines such as IL-17, IL-6, and TNF-α." (PMID 37762693, 2023). "These cytokines promote T cell differentiation into Th1 and Th17, which produce more TNF-α and other proinflammatory cytokines such as IL-17 and IFN-γ, leading to the pathologic manifestations of psoriasis, i.e., keratinocyte hyperproliferation, acanthosis, parakeratosis, and hypogranulosis." (PMID 37546687, 2023). "According to the Psoriasis Longitudinal Assessment and Registry (PSOLAR), malignancy risk increased with long-term exposure to TNF-α inhibitors, but not with exposure to methotrexate or ustekinumab, anti-interleukin 12/23 antibody." (PMID 38276003, 2023). "Besides, SIRT3 governs the production of IL-23 and TNF-α, dominant cytokines in the pathological processes in psoriasis, endowing SIRT3 with higher status in psoriasis than in other inflammatory diseases." (PMID 37275851, 2023). "Interestingly, anti-TNF-α agents used for IBD treatment can induce paradoxical psoriasis due to the hyperactivation of pDCs and their secretion of IFN-γ (IFN secretion is generally inhibited by TNF-α)." (PMID 38003284, 2023). "Real-time PCR results further confirmed that the mRNA levels of psoriasis-related factors keratin-17, integrin β1, and CXCL9, as well as the mRNA levels of inflammation-related factors IL-1β, IL-6, TNF-α and iNOS, were strongly inhibited in skin of Mincleflox/flox/Lyz-cre+/+ mice." (PMID 37117184, 2023). "Both anti-TNF and CsA agents reduced the levels of IFN-c, IL-17A, IL-23p19, and (C–C motif) chemokine ligand 20 in psoriasis lesions, indicating that pro-inflammatory cytokines, particularly IL-17A, are involved in the development of psoriasis." (PMID 36995575, 2023). "Concomitantly, psoriasis patients with depression had higher TNF-a, IL-17A, and IL-23 serum levels than those without depression." (PMID 37240864, 2023). "In fact, many psoriasis patients suffer from diabetes, cardiovascular disease and infectious diseases and are not eligible for treatment with anti-TNF-α or anti-IL-17 drugs." (PMID 37111283, 2023). "Under the condition of abundant IL-23 in psoriasis lesional skin, some macrophages may produce IL-17A, IL-22 and IFN-γ in addition to TNF-α as described in our previous review article." (PMID 38022549, 2023). "On the other hand, the fifth anti-TNF-α agent, certolizumab pegol (CER), is only approved for CD by the United States Food and Drug Administration (FDA) but not by the European Medicines Agency (EMA), though it is used for PsA, RA, SpA, and psoriasis." (PMID 37175894, 2023).
psoriasis (continued). "In a Spanish study involving 70 patients with moderate-to-severe psoriasis, individuals carrying high-affinity genotypes (HH131 + HR131 and VV158 + VF158) showed a greater reduction in BSA at week 6 of anti-TNF-α treatment (beta = 0.372, p = 0.3 and beta = 0.425, p = 0.02, respectively)." (PMID 37372997, 2023). "In the MatTek tissue model of psoriasis, the application of GSH alone resulted in strong inhibition of the expression both of the cell replication marker Ki67 and the inflammatory markers IL17A, IL23, TNF alpha, and TNF beta." (PMID 37469991, 2023). "Notably, agents targeting tumor necrosis factor (TNF), IL-12/IL-23 p40 subunit, IL-17A, and IL-17RA have gained approval for treating psoriasis." (PMID 38137572, 2023). "Moreover, in psoriatic patients have been found elevated levels of inflammatory mediators such as interleukins and tumor necrosis factor-alpha TNF-a, which are the most characteristic circulating inflammatory markers in psoriasis." (PMID 37447169, 2023). "Another study investigated the immunological and genetic profiles of three hidradenitis suppurativa (HS) patients without psoriasis who developed paradoxical psoriasiform reactions following anti-TNF-α therapy with ADA." (PMID 37175894, 2023). "Although the key cytokine leading the outbreak and recalcitrant course of HS is still not definitively known, significantly elevated TNF-α and IL-17 levels in HS lesions compared with healthy control and psoriasis were noticed." (PMID 37242593, 2023). "Currently, biologics targeting TNF-α, IL-12/IL-23 p40, IL-23p19, IL-17A, and IL-36R are used in the clinical treatment of psoriasis, and they are superior in terms of efficacy than nonbiological treatment." (PMID 37762693, 2023). "In osteoarthritis, inflammatory bowel disease, and psoriasis, PGRN can effectively inhibit the inflammatory signaling pathway mediated by TNF-α and reduce the expression of downstream inflammatory factors, thus inhibiting the inflammatory response mediated by TNF-α18." (PMID 38081906, 2023). "It has been reported that circulating S1P levels remain higher in patients with psoriasis than in healthy individuals and that circulating S1P levels do not decrease after anti-TNF-α treatment in those patients." (PMID 37072847, 2023). "Consistent with this, UCA1 was markedly upregulated in primary human epidermal keratinocytes (HEK) and immortalized human keratinocytes HaCaT stimulated with IL17 and/or tumor necrosis factor alpha (TNF-α), which was accompanied by a psoriasis-like inflammatory response (Figure." (PMID 37076497, 2023). "Specifically in inflammatory skin diseases the role of moDCs has been proven in psoriasis, where they produce interleukin (IL)-1β and tumor necrosis factor (TNF) to amplify the inflammatory milieu, but are not solely responsible for it." (PMID 37680639, 2023). "The serum TNF-α and IL-17 levels were increased by the co-occurrence of NASH and psoriasis." (PMID 37646025, 2023). "TNFα inhibitors—The most well-known TNFα inhibitors are infliximab and adalimumab, monoclonal antibodies developed in the last decades to cope with chronic inflammatory disorders such as RA, IBD, psoriasis, psoriatic arthritis." (PMID 36289890, 2022). "Sensing of TNFα and IL22 serum levels using the corresponding receptors and linking their downstream signaling in an AND-gate logic enabled the expression of the anti-inflammatory cytokines IL4 and IL10 to treat psoriasis or prevent its development." (PMID 36225597, 2022). "Also, myeloid cells are important producers of TNF-α, iNOS, and IL-23, which promote the production of IL-17A by CD4+ T cells, and contribute to cardiovascular comorbidities related to psoriasis." (PMID 36741386, 2022). "This amelioration of the lesions induced by pVHL could be explained by negative regulation of the important molecules in psoriasis, such as HIF-1α, VEGF, LDH and TNF-α." (PMID 35563616, 2022).